POSTN (periostin)
Diseases named in the same sentence as POSTN in open-access papers (continued):
Sharing a sentence is not in itself a finding about the gene and the disease.
cancer (continued). "Cytohubba analysis of these genes revealed 13 hub genes, of which MMP13, POSTN, SFRP4, ADAMTS16 and FNDC1 were significantly altered in their expression with CTHRC1 and seen to affect survival across cancers." (PMID 36190948, 2022). "MRNA expression of SPP1, VEGFA, POSTN, CD44, FOXO1, and RUNX2 genes was significantly change with the cancer stages of the patients." (PMID 36424413, 2022). "Multivariate Cox analysis revealed that high stromal periostin overexpression was an independent predictor of overall survival, and LVI and stromal periostin overexpression were independent predictors of cancer-specific survival." (PMID 35850759, 2022). "It would hence be of interest to look at the protein expression data in cancers for CTHRC1 and the now identified genes of interest, POSTN, MMP13, SFRP4, ADAMTS16 and FNDC1." (PMID 36190948, 2022). "The relationship between POSTN expression and VEGF proangiogenic factors is well reported in many cancers." (PMID 36077762, 2022). "Many ECM proteins are associated with the induction of EMT by activating receptor-mediated signaling cascades, such as periostin, thus further strengthening the connection of the TME to cancer progression." (PMID 34200480, 2021). "Collectively, these results demonstrate that the interaction of periostin+CAF‐secreted periostin with endothelial αvβ3 and αvβ5 triggers FAK/Src signaling, consequently promoting lymphatic endothelial permeability and cancer cell intravasation." (PMID 33124726, 2021). "For instances, periostin increases proliferation of cancer cells via activating the ERK pathway, but regulates endothelial cell function via αvβ3 signaling, which implies varying effects of periostin in different cells." (PMID 33124726, 2021). "Unsupervised principal component analysis with the main cancer invasiveness-enriched genes (ASPN, GLT8D2, OLFML2B, CRISPLD2, ADAM12, POSTN, and PRRX1) allowed for the discrimination of subgroups of BMAL1-dependent CRC patients (p = 9.9 × 10−4)." (PMID 34065633, 2021). "The detection of periostin (POSTN) and transforming growth factor beta-induced protein (TGFBI), two circulating biomarkers overexpressed by cancer stem cells, is achieved in cancer patient serum with the use of the device." (PMID 33806753, 2021). "The TCGA and ICGC databases were explored to investigate the involvement of the POSTN protein in the stemness formation and maintenance of HCC cancer cells." (PMID 34193219, 2021). "POSTN was also found to incorporate TNC into the TME and promote stiffening of ECM in the cancer niche, thereby releasing the active form of TGF-β1 regulating cancer cell proliferation via ERK signalling pathway." (PMID 33739025, 2021). "In accordance, HNSCC cancer cells secrete TGF-β3 that enhances POSTN secretion from CAF, resulting in the augmented migratory phenotype of cancer cells." (PMID 34760886, 2021). "As a collective, MMPs, POSTN, TN-C, and other CAF-secreted molecules offer novel therapeutic targets for mitigation of cancer invasion and metastasis." (PMID 33808627, 2021). "POSTN was then found to be induced by various stimuli, including IL-4, IL-13, TNF-β, angiotensin II, connective tissue growth factor 2, BMP-2, and cancer-derived factors." (PMID 34513869, 2021). "POSTN regulates ECM structure and organization by acting on collagen I cross-linking via BMP-1/LOX axis and it is upregulated in a number of cancers." (PMID 31963820, 2020). "On the other hand, POSTN that codes for Periostin, activates the Akt- and FAK-mediated signaling pathways to promote cancer cell motility and the epithelial-mesenchymal transition." (PMID 32079264, 2020). "Laser capture microdissection (LCM) for isolation of stromal and cancer cells of NSCLC was employed, and subsequently, POSTN mRNA expression was detected by real-time PCR." (PMID 32987711, 2020). "Previous studies have also demonstrated periostin as a poor prognostic biomarker in PDAC and other cancers." (PMID 32195182, 2020).
cancer (continued). "While a stable vasculature promotes dormancy, active sprouting neovasculature has been proposed to release cancer cells from the dormant state and support micrometastases growth via TGF-β and periostin." (PMID 32232008, 2020). "We identified several extracellular proteins as up‐regulated in invaded compared to noninvaded nerves (some of these were also seen in PNI compared to non‐PNI cancer), including laminins LAMA2, LAMB1, COL6A3, periostin (POST), nidogen 1 (NID1), and TNC." (PMID 30690892, 2019). "Among the mechanisms that drive EMT, TWIST1 (TW), a bHLH transcription factor and master regulator of EMT, and its transcriptional target periostin (POSTN), a secreted matrix protein, play prominent roles in cancer." (PMID 31540485, 2019). "High levels of POSTN have been also correlated with advanced clinical late stages (III/IV) and cancer recurrence." (PMID 29946533, 2018). "Immunofluorescence analysis revealed that periostin knockdown partially reversed PTX-induced invasive phenotype and MT1-MMP upregulation in E-cadherin- cancer cells." (PMID 29507310, 2018). "In contrast, cell proliferation in the CD44high cancer cells rose significantly 3 days after PTX treatment, and periostin knockdown significantly suppressed this increase." (PMID 29507310, 2018). "Cytokines from cancer cells, especially transforming growth factor-β (TGF-β), increase the periostin secretion from fibroblasts." (PMID 30131847, 2018). "Following periostin treatment, qRT-PCR and Western blot analysis revealed induction of the EMT process by a shift in expression of cancer cells from epithelial (E-cadherin) to mesenchymal phenotypes (N-cadherin, vimentin, and Twist)." (PMID 28977942, 2017). "CAFs also contribute towards cancer cell invasion and metastasis through synthesis of metastasis-promoting ECM proteins such as fibronectin and periostin and the release of matrix metalloproteases." (PMID 28754000, 2017). "However, it is not clear whether periostin is located in cancer cells or cancer-associated stroma or in both compartments." (PMID 29161296, 2017). "Recent research indicates that periostin activates ERK signaling and promotes the cancer stem cell phenotype." (PMID 28977942, 2017). "Collectively, the results of these studies verify that periostin has a pivotal role in PDAC progression and implicate it as a potential biomarker in this cancer." (PMID 29163770, 2017). "To further examine the impact of hypoxia, POSTN expression and TAM infiltration on cancer development, we used Kaplan-Meier estimates to compare survival rates between patients according to their IHC results." (PMID 27602954, 2016). "Periostin (POSTN), a 90-kilodalton secretory protein, has been involved in a number of human cancers including PaC." (PMID 27223086, 2016). "Western blotting was performed to investigate the protein levels of POSTN in HNC tissues and the results indicated that POSTN was highly expressed in cancer samples compared with adjacent normal tissues." (PMID 26857387, 2016). "Periostin (POSTN) is a component of the extracellular matrix that has been identified in the niche of both normal and cancer stem cells." (PMID 27058560, 2016). "Breast cancer cells, in turn, secrete periostin that sequesters DCN and by doing so the cancer cells provide themselves an opportunity to grow invasively and migrate without inhibitory activity from DCN." (PMID 26697491, 2015). "Disruption of periostin signalling via integrin receptors and the PI3K–Akt pathway leads to abrogation of cancer cell invasion." (PMID 25345775, 2015). "The findings suggest that periostin has concentration-dependent dual effects on the development of pancreatic cancer, especially on EMT and migration of the cancer cells." (PMID 26029109, 2015). "To determine the correlation between periostin and VEGF-C expression levels in clinical cancer cases, we compared periostin expression with VEGF-C expression in 54 HNSCC cases by immunohistochemical analysis." (PMID 22952986, 2012).
cancer (continued). "Moreover, the VEGFR-3 kinase inhibitor inhibited the tube formation induced by conditioned medium from periostin-overexpressing cells, suggesting that periostin-promoted lymphangiogenesis may be caused in part by increased secretion of VEGF-C from cancer cells." (PMID 22952986, 2012). "Periostin interacts with multiple cell-surface receptors (most notable integrins) and signals via the PI3-K/Akt and other pathways to promote cancer cell survival, epithelial-mesenchymal transition, invasion, and metastasis." (PMID 22110952, 2011). "Periostin (POSTN) is a secreted extracellular matrix protein of poorly defined function that has been related to bone and heart development as well as to cancer." (PMID 20109226, 2010). "But there is also mounting evidence that periostin and TGFBI can have complementary or opposite roles in cancer and development." (PMID 20109226, 2010). "Our data indicate that the expression of periostin in the CAFs was not correlated with potentially aggressive cancer characteristics that are present at stage 2 and showed a relationship only at stage 3." (PMID 39941916, 2025). "RNA-seq analysis revealed elevated levels of the extracellular matrix proteins periostin and CTGF in the heart and serum of mice after TAC; both of these proteins are known to influence cancer cell behavior, including proliferation, migration, and epithelial-to-mesenchymal transition." (PMID 39634266, 2024). "Furthermore, their research highlights the direct stimulation of cancer cell growth, migration, and invasion through TGF‐β3‐induced upregulation of Periostin expression." (PMID 38946720, 2024). "While the Gla protein family is primarily recognized for its significance in bone metabolism and calcification, recent studies have highlighted the vital roles played by Periostin and MGP in ECM metabolism, inflammation, fibrosis, allergic diseases, and cancer." (PMID 38946720, 2024). "Additionally, we explored the relationship between POSTN expression and immune cell infiltration, as well as the immunophenoscore (IPS), by leveraging the cancer immunome atlas (TCIA) database." (PMID 38389400, 2024). "We transfected this oligo to 4T1 mice TNBC cells and proved that the pathological POSTN with exon 17 inhibition in cancer but not stroma noticeably suppressed metastasis." (PMID 39272982, 2024). "This analysis demonstrated that expression of POSTN was observed predominantly in fibroblasts and smooth muscle cells, but not in cancer cells." (PMID 38389400, 2024). "POSTN is a non-structural extracellular matrix (ECM) protein, which is synthesized by both cancer cells and cancer-associated fibroblasts (CAFs)." (PMID 39272978, 2024). "Due to variations between datasets, FABP4 expression did not predict patient disease-free survival in the TCGA Firehose Legacy dataset, while U2AF2, RUVBL1, XPO1, and POSTN did not predict disease-free survival in the BS Taylor, Cancer Cell, 2010 dataset." (PMID 39402324, 2024). "Furthermore, the expression of QPCTL was positively correlated with SAA1, POSTN, PLA2G2A, SAA2,C6orf15, H19, PI3, etc., whose expression also affects cancer progress." (PMID 37063864, 2023). "We suggest that a novel cancer‐specific POSTN isoform lacking exon 17 (Iso5) can be a useful marker for detecting cancer cells undergoing p‐EMT." (PMID 36691359, 2023). "In triggering cancer cell reactivation after dormancy, the important players are: endothelial cells from neovasculature that produce TGF-β1 and periostin; adipocytes via FABP4; macrophages with cathepsin K; and protein in the microenvironment, such as type 1 collagen and fibronectin." (PMID 36900309, 2023). "Additionally, POSTN and lysyl oxidase-like 1 (LOXL1) overexpressed by CAFs degrade the basement membrane and stromal ECM and initiate the invasion of malignant tumors." (PMID 37234990, 2023).
cancer (continued). "Although collagen inhibition has been shown to increase the infiltration of cytotoxic T cells into tumors of various cancers, there is no study showing the effect of periostin on the infiltration of NK cells in the literature." (PMID 36830807, 2023). "Targeting the factors that enhance CSC numbers, such as periostin in the TME, could provide a mechanism for reversing therapy resistance and reducing cancer recurrence." (PMID 38049490, 2023). "Functional analysis indicated that the highly-expressed FAP in these cancers could affect extracellular matrix organization process and interacted with genes like COL1A1, COL1A2, COL3A1 and POSTN." (PMID 37325617, 2023). "Recent evidence showed that POSTN, a component of the extracellular matrix (ECM) produced by fibroblasts in the stroma of primary tumors, plays a critical role in the formation and remodeling of cancer tissue microenvironments." (PMID 36765564, 2023). "For example, cSCC, the second most common type of non-melanoma skin cancer, was shown to express POSTN in cancer fibroblasts (CAFs), which correlated with the aggressiveness of their biological nature." (PMID 35409404, 2022). "The process of alternative folding of POSTN is generally understood, as opposed to the role of the isolated isoforms of the protein in the progression and metastasis of cancer cells." (PMID 36077762, 2022). "We noticed a markedly higher level of POSTN mRNA expression in microdissected cancer cells compared to non-malignant lung cells (NMLC)." (PMID 35163164, 2022). "Our results confirmed the increased expression of POSTN in cancer cells of NSCLC compared to NMLT, suggesting that POSTN could be related to the process of carcinogenesis in NSCLC." (PMID 35163164, 2022). "Of note, periostin promotes chemoresistance through several mechanisms, including: 1-induction of EMT; 2-increased cancer cell stemness; 3-upregulation of LOX and increasing stiffness; 4-activation of Akt and Erk, the PI3K/Akt/survivin, and the PI3K/Akt/survivin pathways." (PMID 36224629, 2022). "It is believed that POSTN may act as a mediator to stimulate TGF-β1 to promote EMT and metastasis formation in some cancers." (PMID 36077762, 2022). "Moreover, we detected the effect of POSTN silencing on MMP activity, which was correlated with basement membrane degradation and cancer cell invasion." (PMID 35163164, 2022). "Periostin expression is reported to be negative or low in most cancer cell lines, and only a small number of cell lines show high or moderate expression." (PMID 36224629, 2022). "Periostin could be involved in metastasis through ECM remodeling, premetastatic niches, cancer stem cell niches, and perivascular niches formation and also fibrotic microenvironment establishment." (PMID 36224629, 2022). "POSTN has been shown to signal through the PI3K/Akt and Src pathways in various cancers." (PMID 35884543, 2022). "However, we focused on the detection of the periostin POSTN and transforming growth factor beta-induced protein TGFBI proteins, which, in cancer cells, are regulated by the stem cell transcription factor Snail (SNAI1)." (PMID 33806753, 2021). "When the cancer EVs were applied to the fibroblasts directly, the effects on tenascin-C expression were similar to those of the conditioned medium, and the fibroblast activation markers α-SMA and periostin were also upregulated." (PMID 34564696, 2021). "When cancer cells were cultured in serum-free media with or without rh-periostin, rh-periostin increased the growth of cancer cells under both 2D and 3D conditions." (PMID 34702952, 2021). "Interestingly, several genes were known to be regulated by the TGFβ pathway (e.g., BMF, COL4A4) and/or expressed in several cancers (e.g., HOTAIR, MRC2, POSTN, SPARC)." (PMID 34830779, 2021).
cancer (continued). "In this study, we found that the POSTN short fragment containing exon 17 but not exon 12 and primarily originates from fibroblasts, was cleaved from its N-terminal region and accumulated in the cancer cell ECM, while the POSTN fragment containing exon 12 remained in the stroma." (PMID 33919736, 2021). "Despite the elevated levels of periostin in human cancers, this glycoprotein has not been utilized as a biomarker due to variable expression in inflammatory conditions." (PMID 30911061, 2019). "The correlation between POSTN and ANRIL was found when only tumors with nuclear ANRIL were included, suggesting the subcellular localization of ANRIL will be important in determining the potential effects of ANRIL toward cancer progression." (PMID 31572679, 2019). "Despite the high expression in human cancer tissues, human cancer cell lines grown under adherent growth conditions do not express periostin." (PMID 30911061, 2019). "It was suggested that the level of stromal POSTN could be induced by TGF‐β3, leading to accelerated growth, migration and invasion of cancer cells." (PMID 31304688, 2019). "In the primary site, periostin was detected in fibroblasts adjacent to cancer cells in periostin+/+ mice, while no periostin-positive fibroblasts were observed in periostin−/− mice." (PMID 30131847, 2018). "Periostin expression was either absent or low positive in IBC cancer cells, while highly positive in cancer-associated stroma in almost all cases." (PMID 29161296, 2017). "Immunohistochemical staining indicated that high levels of periostin were present in the mesenchymal areas, but not in the cancer cells themseleves." (PMID 28088789, 2017). "POSTN also functions as a driver of EMT and induces expression of matrix metalloproteinase (MMP)-9, -10, and -13, resulting in the degradation of extracellular matrix (ECM), and promoting cancer spread and metastasis." (PMID 26556874, 2016). "Hence, our study has provided a novel modulative role for POSTN on HNC progression and further reveals POSTN as an effective biomarker to predict metastasis as well as a potential cancer therapeutic target." (PMID 26857387, 2016). "Periostin is highly expressed by PSC and its level may be a key regulator of the pro-EMT/cancer and the anti-EMT/cancer effects of PSC." (PMID 26029109, 2015). "Interestingly, TGFb3 is a known inducer of both periostin and NEDD9, both of which have been reported as frequently overexpressed in a variety of human cancers." (PMID 23372733, 2013). "Immunostaining indicated that high levels of periostin were present in the mesenchymal areas, but not in the cancer cells themselves." (PMID 24273600, 2013). "This metastatic colonisation by cancer cells largely depends on the support provided by the stromal niche, which is created by a unique composition of local stromal environmental factors including ECM periostin (POSTN) and tenascin-C (TN-C) proteins." (PMID 24216702, 2013). "The immunostaining indicated that high levels of periostin were present in the mesenchymal areas, but not in the cancer cells themselves." (PMID 24273600, 2013). "Several studies have indicated that Periostin mRNA and protein are not expressed in several human cancer cell lines." (PMID 21714934, 2011). "Some studies demonstrate that Periostin overexpression does not promote proliferation of human cancer cell lines including 293T, B16F1,MDA-MB-231,HSC2 and HSC3." (PMID 21714934, 2011). "ECM-related genes that promoted the strongest proliferation, including POSTN, BGN type I collagen and type IV collagen, have already been identified as cancer markers, and might be molecular targets for gene therapy." (PMID 17411443, 2007). "Our comparative analysis suggests that, although periostin overexpression is clearly detected in some cancers, it is not a general feature of tumors." (PMID 18086302, 2007).